AR (androgen receptor)
Diseases named in the same sentence as AR in open-access papers (continued):
Sharing a sentence is not in itself a finding about the gene and the disease.
prostate carcinoma (continued). "Collectively, these data strongly suggest that MDM2 E3 ligase activity diminishes the protein levels of both AR and TM4SF3 in prostate cancer cells." (PMID 38410785, 2024). "As AR inhibitor ENZ is known to induce t-NEPC, we first exposed LNCaP and C42B prostate cancer cells to ENZ and monitored the expression of DPYSL5 and neuronal lineage markers every three days over a total of twelve days." (PMID 38238517, 2024). "The well‐known AR target genes TMPRSS2 and FKBP5 show enhanced chromatin accessibility, as assessed by ATAC signals, in prostate cancer samples (TCGA‐PRAD)." (PMID 38483933, 2024). "By inferring the Decipher prognostic gene signature in the prostate cancer dataset (GSE116918), differences in fibroblast cells, androgen receptor (AR), and MYC proto-oncogene (MYC) TF activity between the two patient subgroups are observed." (PMID 39574035, 2024). "Combining existing reports with the analysis presented in this study, it can be inferred that RORC, AR, LIN28B, IRF9, and IRF3 promoted prostate cancer lineage plasticity through the RTK/RAS pathway." (PMID 38778150, 2024). "Through androgen receptor signaling inhibitor (ARSI) treatment, patients eventually succumb to castration-resistant prostate cancer (CRPC)." (PMID 39175878, 2024). "We further showed that degradation of these subunits, along with PBRM1, led to rapid and widespread chromatin compaction, perturbing essential oncogenic programs driven by transcription factors such as AR, FOXA1, and ERG in prostate cancer models." (PMID 38557192, 2024). "To date, several substances have been developed to target the AR signaling axis, and some of them are used clinically for BPH and prostate cancer." (PMID 39830338, 2024). "Furthermore, by acting as AR antagonists, the studied cannabinoids may also be attractive for other pathological conditions where AR antagonists could be clinically applied, such as prostate cancer and benign prostatic hyperplasia." (PMID 39338407, 2024). "Interestingly, the A646D mutation is reported to reduce AR:SPOP affinity and is frequently observed in patients with partial androgen insensitivity syndrome (PAIS), mild androgen insensitivity syndrome (MAIS), and prostate cancer (COSMIC legacy identifier- COSM6906185)." (PMID 38667288, 2024). "Androgen receptor (AR) pathway inhibition (ARPI) triggers strong and lasting responses in advanced prostate cancer." (PMID 39239525, 2024). "Oncolytic viruses (mammalian orthoreovirus) can also be employed to selectively target prostate cancer cells through HIF-1α inhibition, inducing apoptosis and downregulation of Akt, AR and PSA." (PMID 39840030, 2024). "In summary, our study demonstrates a previously unrecognized function of AR inhibiting ROS accumulation by upregulating PEX10 and suggests a new strategy of using enzalutamide in prostate cancer treatment." (PMID 39097593, 2024). "The androgen receptor (AR) is vital to the development and progression of metastatic CRPC through AR reprogramming and maintains the growth of prostate cancer cells in an androgen‐depleted state." (PMID 38605607, 2024). "In prostate cancer cells, TBL1XR1 played an essential role in AR-mediated transcription and there was physical interaction between TBL1XR1 and AR." (PMID 38347836, 2024). "In the context of castration-resistant prostate cancer, the patient was subsequently maintained on continuous ADT and androgen receptor antagonists (enzalutamide) following the palliative penectomy." (PMID 39868372, 2024).
prostate carcinoma (continued). "Together, aberrations in PSA levels, AR signaling, and NKX3-1 expression provide growth advantages to prostate cancer cells, while also serving as useful biomarkers of disease status and potential therapeutic targets." (PMID 39201018, 2024). "It inhibits androgen receptor (AR) and prostate-specific antigen (PSA) activity, crucial in prostate cancer etiology." (PMID 39199550, 2024). "It has been reported that bufalin can induce caspase-mediated cell apoptosis and decrease the levels of SRC-1, AR, and its target gene PSA, exerting an anti-prostate cancer effect." (PMID 38553750, 2024). "The standard of care for advanced prostate cancer (PCa) consists of Androgen Deprivation Therapy (ADT) and the use of ever more effective therapies targeting the androgen receptor (AR) under different mechanisms." (PMID 39199688, 2024). "Previous studies showed that AR binds to genomic regions of TMPRSS2 and ERG and facilitates chromosomal translocation in prostate cancers." (PMID 39139449, 2024). "The AR, a member of the steroid receptor family, is a ligand-dependent transcription factor that mediates androgen and DHT in prostate cancer cells." (PMID 38474045, 2024). "In mouse prostate cancer xenografts, POM121 drives tumor progression through importin-β-dependent nuclear import of androgen receptor, E2F1 and MYC, whereas importin-β inhibitor importazol attenuated tumor growth." (PMID 38177114, 2024). "Nevertheless, samples processed with VTX-1 allowed us to detect AR with AdnaDetect in almost all cases, many of which were also positive for PSMA, indicating the presence of prostate cancer CTCs at sufficient purity." (PMID 38627648, 2024). "The pleiotropic effects of CDKI-73 likely have important ramifications for prostate cancer treatment: i) they may mitigate the ability of cancer cells to effectively develop resistance mechanisms; and ii) they would be expected to potentiate the activity of standard-of-care AR-targeted therapies." (PMID 39117800, 2024). "Quercetin inhibits the function of AR; reduces the secretion of PSA, HK2, and androgen-regulated tumor biomarkers; and regulates apoptosis in prostate cancer." (PMID 39062777, 2024). "In prostate cancer, DTHIB surpasses enzalutamide in reducing cell viability, inhibiting androgen receptor signaling, and suppressing PSA expression." (PMID 38339390, 2024). "BET inhibitors are emerging as a potential treatment for advanced prostate cancers due to their potential impact on both MYC expression and the AR." (PMID 38379333, 2024). "In an in vivo experiment using a CWRSA6 prostate cancer xenograft, the administration of 17-AAG at 50 mg/kg reduced AR expression by 80%." (PMID 38339414, 2024). "Despite various treatment options such as androgen receptor-directed therapies, taxane-based chemotherapy, PSMA radioligand therapy, radium-223 and PARP inhibitors, prostate cancer in the castration-resistant situation takes a fatal course." (PMID 38783016, 2024). "MDM2 inhibition by siRNA depletion or using a pharmacological inhibitor (MDM2i) of its E3 ligase activity led to elevated levels of endogenous AR, AR-V7, and TM4SF3 in prostate cancer cells." (PMID 38410785, 2024). "Recent research published in 2024 led to the discovery that ALDH1A1 promotes metastasis and treatment resistance in prostate cancer through interactions with RAR-dependent transcription and the androgen receptor (AR)." (PMID 39796106, 2024). "In a meta-analysis by Itkonen and colleagues, GUCY1A1 was identified as an AR- and ERG-upregulated target involved in the hexosamine biosynthesis pathway (HBP), which is overexpressed in clinical cases of prostate cancer." (PMID 39337539, 2024). "This study reveals a previously unrecognized function of enzalutamide and AR by regulating PEX10 and suggests a new strategy of enzalutamide application in prostate cancer treatment." (PMID 39097593, 2024).
prostate carcinoma (continued). "Utilization of our patient-specific prostate cancer Boolean networks revealed the potential role of prolonged AR therapy in inducing gene expression changes in TGF-β, IDH1, and cell cycle pathways specifically in prostate cancer of AA men." (PMID 38566104, 2024). "Further to its role in prostate cancer in directly binding the AR and maintenance of membrane localised PMSA filamin A cleavage by calpain represses tumour metastasis in AR-positive prostate cancer, and its subcellular localisation is key to this." (PMID 38958472, 2024). "Further, we demonstrate that this chromatin-altering property of SHP2 drives a diverse spectrum of disorders such as prostate cancer and NSML by regulating androgen receptor (AR) transcriptome." (PMID 38965223, 2024). "AR signaling also interacts with other pathways, such as PI3K/AKT, MAPK, and Wnt/β-catenin, which can modulate its activity and contribute to prostate cancer progression." (PMID 39184676, 2024). "In breast and prostate cancer models, p300-mediated H3K27 and receptor acetylation determines estrogen receptor expression and androgen receptor (AR) stability, respectively." (PMID 38949020, 2024). "BAG-1L plays a critical role in transactivation of the AR and nuclear BAG-1 protein expression correlates with important clinical characteristics in prostate cancer." (PMID 38412481, 2024). "In prostate cancer, EZH2 is known to collaborate with AR in promoting the progression of AR-positive CRPCs through both H3K27me3-dependent and -independent mechanisms." (PMID 38777812, 2024). "Additionally, while targeted forms of therapy exist that can be used for metastatic CRPC, we must continue to identify cancer-associated markers for the treatment of prostate cancers that have a resistance to hormone therapy and no androgen receptor (ARneg-AI prostate cancer)." (PMID 39000112, 2024). "In the context of prostate cancer, the CRISP3 promoter is regulated by the androgen receptor (AR) through an epigenetic mechanism, and CRISP3 expression is induced by the presence of dihydrotestosterone (DHT) in AR-positive cells." (PMID 39139989, 2024). "In recurrent prostate cancer, the expression of DAB2IP is inversely correlated with androgen receptor activation, and DAB2IP expression in PCa cells can suppress androgen-induced cell proliferation and gene activation." (PMID 38902547, 2024). "In prostate cancer, MSI2 can bind to the 3’-UTR region of androgen receptor (AR) mRNA, enhancing its mRNA stability and translation activity, and regulating the PI3K/AKT/mTOR pathway." (PMID 39097735, 2024). "In prostate cancer, etomoxir suppressed cell growth by reducing both FAO and androgen receptor expression levels." (PMID 38610991, 2024). "ADT resulted in the predominance of these more value-adding AR-positive neuroendocrine cells, leading to rapid resistance to endocrine therapy and the development of NEPC in prostate cancer." (PMID 39655078, 2024). "Systematic evaluation of licochalcone A across four prostate cancer cell lines indicated a modest advantage over enzalutamide, an FDA-approved AR antagonist, in suppressing 22Rv1 cell proliferation." (PMID 39770110, 2024). "In prostate cancer, CREB3L4 is considered to facilitate the prostatic cancer cell proliferation via interacting with the androgen receptor." (PMID 38303702, 2024). "Here, the study reports a novel cereblon‐based AR degrader, UBX‐390, and demonstrates its superior activity over established AR degraders, such as ARV‐110 or ARCC‐4, in prostate cancer cells under short‐ and long‐term treatment conditions." (PMID 38958553, 2024). "In this study, we demonstrated that MA, a small molecule inhibitor from a marine sponge, represses AR transcription via the atypical E2F transcriptional factor E2F8 and inhibits prostate cancer cell proliferation in vitro and in vivo." (PMID 38605607, 2024).
prostate carcinoma (continued). "It has been demonstrated that in androgen-dependent prostate cancer cells, upregulation of MUC1-C inhibits androgen receptor (AR) signaling and drives the expression of the neurotranscription factor BRN2." (PMID 38780447, 2024). "While it was initially thought that PSMA expression is controlled largely by AR, more recent findings have identified HOXB13 as an upstream regulator for PSMA expression in both AR+ and AR- prostate cancer lesions." (PMID 39273701, 2024). "We examined the correlation between the gene expression level of AR and YAP1 in TCGA prostate cancer database (n = 498)." (PMID 39149855, 2024). "We next determined the significance of NURR1 overexpression in castration-relapse growth of prostate cancer cells using an established xenograft model of CRPC, that is based on the castration-relapse growth of AR-positive VCaP cells." (PMID 38531859, 2024). "This study identifies MDM2 as a potential common E3 ligase for AR, AR-V7, and TM4SF3 in prostate cancer cells and suggests a novel mechanism for the mutual stabilization of TM4SF3 with AR or AR-V7 by disrupting the action of MDM2 on these proteins." (PMID 38410785, 2024). "PLK1 is elevated in prostate cancer and plays a role in coordinating the downstream PI3K-AKT-mTOR pathway and the activation of AR signaling through elevating cholesterol biosynthesis during the progression to castration-resistant disease." (PMID 38201308, 2024). "Glucose transporters GLUT1 and GLUT2 are regulated at the transcriptional level by the AR, whereas control by AR-independent factors such as SOX2 and MYC promotes prostate cancer progression, lineage plasticity, and therapy resistance." (PMID 38969865, 2024). "In the network pharmacology analysis, 32 targets of Sappan lignum against prostate cancer were identified, including SRD5A2, which is closely related to the androgen receptor (AR)." (PMID 39318781, 2024). "Genes regulated by AR, such as KLK2, NKX3.1, and KLK3 (PSA), are extensively studied in prostate cancer." (PMID 38791417, 2024). "Treatment of enzalutamide-resistant prostate cancer cells with inhibitors of either p300 or BET was shown to destabilize KDM3A, conferring sensitivity to the AR antagonist." (PMID 39394462, 2024). "In prostate cancer cells, HSP90 interacts with AR-FL and AR-V7 and sustains their stability and ligand-binding ability, and HSP90 expression correlates with PCa progression and the levels of AR-FL and AR-V7." (PMID 39567496, 2024). "In this study, we found that inhibiting MDM2, either by siRNA or a pharmacological inhibitor of its RING domain, increased levels of AR, AR-V7, and TM4SF3 protein in prostate cancer cells, leading to elevated growth of these cells." (PMID 38410785, 2024). "lncRNA-HOTAIR from the HOXC genome is significantly increased in prostate cancer cell lines, and HOTAIR binds to AR proteins to block their interaction with the E3 ubiquitin ligase MDM2, thereby preventing AR ubiquitination and protein degradation." (PMID 39655078, 2024). "The resulting drug, Au-AR pep-PROTAC, efficiently degrades AR-FL and AR-V7 in prostate cancer cells, leading to tumor regression in both sensitive and resistant mouse models." (PMID 38201308, 2024). "Expression of the AR on CD8+ T cells is known to promote T cell exhaustion in colorectal cancer, cutaneous melanoma, and prostate cancer." (PMID 38949020, 2024). "In prostate cancer, HSP90 regulates the activity and stability of the AR by forming the HSP90-AR complex." (PMID 38339390, 2024). "Although SRC-1 has demonstrated effective interactions with AR and ERα, the majority of studies have focused on how AR-SRC-1 influences cell proliferation during prostate development and in prostate cancer." (PMID 39596206, 2024). "After androgen deprivation, prostate cancer frequently becomes castration resistant (CRPC), with intratumoral androgen production from extragonadal precursors that activate the androgen receptor pathway." (PMID 37009898, 2023).
prostate carcinoma (continued). "In this study, we found that ADT resulted in loss of the tumor suppressor effect of AR and reduced binding of AR to the CHRM4 regulatory sequence, thereby enhancing CHRM4 expression in prostate cancer cells." (PMID 37142586, 2023). "The newly added in mechanism not only enhances our understanding of the clinical effectiveness of docetaxel and cabazitaxel in treating AR-driven CRPC, but also opens up possibilities for exploring improved treatments for various forms of prostate cancer." (PMID 37444418, 2023). "By modulating FGF11, miRNA-541, androgen receptor (AR), and MMP9 signaling, infiltrating T cells increase prostate cancer metastasis." (PMID 37250453, 2023). "AR-SVs, including AR-V7, are expressed in ~30% of CRPC, but minimally in treatment-naïve primary prostate cancer (PCa)." (PMID 36979627, 2023). "Specifically in prostate cancer, our previous work revealed that LSD1 promotes AR-independent survival of both adenocarcinoma and DNPC cells." (PMID 37440313, 2023). "In advanced prostate cancer, the excessive production of GABA has been reported to directly modulate nuclear androgen receptor signals, thereby contributing to tumorigenesis." (PMID 38104097, 2023). "In prostate cancer, HSP70 plays an important role in inhibiting cell apoptosis, cell cycle regulation, metastasis, and AR transcriptional activity and stability." (PMID 36773708, 2023). "EZH2 overexpression promotes castration resistance in prostate cancers via various mechanisms, including inducing epithelial-to-mesenchymal transition (EMT), increased stem cell potential, and androgen receptor pathway activation." (PMID 37104249, 2023). "Paclitaxel was then found to suppress the subsequent AR transcriptional activity, as characterized by the ARE (androgen response element) luciferase reporter vector in LNCaP prostate cancer cells." (PMID 37444418, 2023). "AR signaling plays a pivotal role in the development and growth of the normal prostate, BPH (benign prostatic hyperplasia) and prostate cancer." (PMID 36674820, 2023). "In prostate cancer, KLF5 interacts with androgen receptor (AR) and contributes to cancer development stimulated by AR signaling." (PMID 37181807, 2023). "This study proposed a new screening method for the detection of AR function inhibitors and identified DNT as a possible anti-prostate cancer agent." (PMID 37744273, 2023). "Previous literature has indicated that AR and MYC become co-regulators in prostate cancer, but only as a function of disease progression." (PMID 37059746, 2023). "AR knockdown enhanced DTX‐induced cell apoptosis and cell cycle arrest at the S phase in prostate cancer cells, which was attenuated by FEN1 overexpression." (PMID 37326412, 2023). "Although we have studied the role of AR and FEN1 in prostate cancer extensively and confirmed the non‐genomic regulatory mechanism of AR on FEN1, there are still several limitations to this work which should be emphasised." (PMID 37326412, 2023). "Enzalutamide and the more efficient AR antagonist apalutamide appear to be good candidates to limit SARS-CoV-2 infection and should be tested with local treatment in the prostate cancer population vulnerable to severe COVID-19." (PMID 36834705, 2023). "In prostate cancer cells, SFN inhibits HDAC6 activity, increasing the level of acetylation in heat shock protein 90 (Hsp90) and decreasing androgen receptor (AR) expression." (PMID 37298289, 2023). "Other studies highlighted the oncogenic function of the methyltransferase EZH2 in castration-resistant prostate cancer cells, where EZH2 acts as a coactivator for critical transcription factors, including the androgen receptor." (PMID 37894361, 2023).